PROK1 (prokineticin 1)
Description:
Potently contracts gastrointestinal (GI) smooth muscle. Induces proliferation, migration and fenestration (the formation of membrane discontinuities) in capillary endothelial cells derived from endocrine glands. Has little or no effect on a variety of other endothelial and non-endothelial cell types. Induces proliferation and differentiation, but not migration, of enteric neural crest cells. Directly influences neuroblastoma progression by promoting the proliferation and migration of neuroblastoma cells. Positively regulates PTGS2 expression and prostaglandin synthesis. May play a role in placentation. May play a role in normal and pathological testis angiogenesis.
Synonyms: EG-VEGF; PK1; PRK1; EGVEGF
Tractability: Antibody: its Gene Ontology location is reachable by antibodies, with high confidence; UniProt places it where antibodies can reach, with medium confidence; UniProt predicts a signal peptide or a membrane-spanning region.
Gene: Protein-coding gene on chromosome 1 (110,451,149 to 110,457,358, forward strand). Ensembl gene ENSG00000143125.
Subcellular location: Secreted
Pathways (Reactome):
Signal Transduction: G alpha (q) signalling events; Peptide ligand-binding receptors
Gene Ontology:
Biological process: endothelial cell proliferation
Cellular component: extracellular region
Genetic constraint (gnomAD): Loss-of-function variants: 12 observed, 11.58 expected, observed/expected ratio (o/e) 1.04, 90% interval 0.66 to 1.65. The upper end of that interval is the gene's LOEUF score, 1.65, which puts it in group 6 of 6, group 1 being the genes least tolerant of losing a copy. Missense variants: 140 observed, 145.68 expected, observed/expected ratio (o/e) 0.96, 90% interval 0.84 to 1.11. Synonymous variants: 57 observed, 59.42 expected, observed/expected ratio (o/e) 0.96, 90% interval 0.77 to 1.2.
Homologues: Orthologues: chimpanzee PROK1 (100% identical), macaque PROK1 (96% identical), guinea pig PROK1 (90% identical), dog PROK1 (89% identical), pig PROK1 (85% identical), mouse Prok1 (84% identical), rabbit PROK1 (83% identical), tropical clawed frog PROK1 (70% identical), zebrafish prok1 (65% identical), rat Prok1 (61% identical). Paralogues in human: PROK2 (49% identical).
Diseases named in the same sentence as PROK1 in open-access papers:
PROK1 is named in the same sentence as 40 diseases in open-access papers, as found by Europe PMC text mining. Sharing a sentence is not in itself a finding about the gene and the disease. The quoted sentences say what the papers report.
colorectal cancer (8 papers, 2015 to 2023). A primary or metastatic malignant neoplasm that affects the colon or rectum. "In conclusion, PROK1 expression in the plasma was associated with poor prognosis in patients with colorectal cancer who underwent R0 resection." (PMID 34657605, 2021). "The present study aimed to examine the association between preoperative PROK1 concentration in the plasma of patients with colorectal cancer and their prognosis." (PMID 34657605, 2021). "In our study, we revealed the association between plasma PROK1 expression and cancer-related survival rate in colorectal cancer patients undergoing R0 resection." (PMID 34657605, 2021). "This study showed the possibility of using PROK1 as a high-risk marker for stage III colorectal cancer." (PMID 34657605, 2021). "In terms of PROK1 concentration in the plasma, one study reported that PROK1 expression in the plasma was associated with peritoneal carcinomatosis in colorectal cancer." (PMID 34657605, 2021). "This study investigated the association between plasma PROK1 expression and prognosis in patients with colorectal cancer undergoing R0 resection." (PMID 34657605, 2021). "This study investigated the association between PROK1 concentration in plasma and prognosis in colorectal cancer patients." (PMID 34657605, 2021). "Although the association between PROK1 expression in primary cancer lesion and patient prognosis was reported, it is unclear whether plasma PROK1 concentration may be a predictive factor in colorectal cancer patients." (PMID 34657605, 2021). "Overall, these results suggest that the proliferation of colorectal cancer cells was suppressed in the anti-PROK1 antibody-treated group." (PMID 38275664, 2023). "Over the years, our laboratory has reported the involvement of PROK1 in tumor growth, angiogenesis, and infiltration in colorectal cancer." (PMID 38275664, 2023). "In this study, a liver metastasis mouse model was developed using human colorectal cancer cell lines, and mice were divided into anti-PROK1 antibody administration and control groups." (PMID 38275664, 2023). "The anti-PROK1 antibody developed by our group suppressed liver metastatic lesions in a mouse model of colorectal cancer with liver metastasis." (PMID 38275664, 2023). "The number of lymph vessels was 20.5 per visual field in the skin tissue adjacent to subcutaneously injected high-expressing-PROK1 DLD1 colorectal cancer cells, and there were 13.5 per visual field when the anti-PROK1 antibody." (PMID 34262649, 2021). "PROK1 expression was found in the primary lesion of 142 of 391 (36%) colorectal cancer patients who had undergone resection in our department." (PMID 34262649, 2021). "The number of lymph vessels was 19.5 per visual field in the skin tissue adjacent to subcutaneously injected high-expressing-PROK1 LoVo colorectal cancer cells." (PMID 34262649, 2021). "The mRNA expression of PROK1 showed poor prognosis in colorectal cancer, while 36% of primary cancer lesions were positive for PROK1 in immunohistochemistry, leading to a poorer prognosis." (PMID 34657605, 2021). "We previously reported, for the first time, that the increase of PROK1 is relevant to angiogenesis and hepatic metastasis of colorectal cancer cells in patients." (PMID 34262649, 2021). "The role of PROK1 in the tumor microenvironment has been revealed by the present study, which leads the development of a new therapy for colorectal cancer by providing basic insight for the molecular mechanism of invasion and metastasis." (PMID 34262649, 2021). "We report here that PROK1 is involved in angiogenesis and hematogenous metastasis, including hepatic metastasis, in colorectal cancer." (PMID 34262649, 2021). "The high-PROK1-expressing colorectal cancer cell line was found to extracellularly secrete PROK1, and lymphangiogenesis was suppressed using the anti-PROK1-antibody." (PMID 34262649, 2021).
colorectal cancer (continued). "PROK1 expression in preoperative plasma reflects poor prognosis in patients undergoing curative resection for colorectal cancer." (PMID 34657605, 2021). "Prokineticin 1 (PROK1) was reported as an angiogenic factor, which is associated with tumor progression, cell invasion, and metastasis in colorectal cancer." (PMID 34657605, 2021). "This indicates that in colorectal cancer, the tumor itself organizes the surrounding environment via PROK1 expression, which plays an important role within the tumor microenvironment." (PMID 34262649, 2021). "PROK1 has been shown to exert promoting tumor progression, invasion, and metastasis in colorectal cancer." (PMID 34657605, 2021). "And PROK1 is thought to work as an angiogenic growth factor in colorectal cancer and to be involved in autocrine mechanism-induced infiltration of cancer cells." (PMID 25788276, 2015). "The prognosis was poorer in colorectal cancers that expressed both PROK1 and VEGF relative to the cases that expressed only 1 protein, and the expression of both proteins was found to be an independent prognostic factor." (PMID 26318037, 2015). "It was recently found that PK-R2, a receptor for PROK1, was expressed in the same colorectal cancer cell strain, playing a role in cellular invasion via autocrine signaling induced by PROK1." (PMID 26372733, 2015). "Immunohistochemical staining showed PROK1/VEGF expression in the human colorectal cancer cell lines LoVo, HCT116, and DLD-1." (PMID 25788276, 2015). "The 5-year survival rates for Stage III colorectal cancer patients were 84.4% among cases that expressed either VEGF or PROK1 protein, and 59.1% among cases that expressed both proteins." (PMID 26318037, 2015). "We further found that tumor growth, hepatic metastasis, and angiogenesis were induced when PROK1 was strongly expressed in a low-PROK1 expressing colorectal cancer cell strain." (PMID 26372733, 2015). "According to recent findings, an anti-PROK1 antibody suppressed angiogenesis in a PROK1 receptor-expressing colorectal cancer subset, and the infiltrative ability of these cells was promoted by an autocrine PROK1 mechanism." (PMID 26318037, 2015). "Recently we found that PROK1 protein was observed in the culture fluids of all colorectal cancer cell lines: DLD-1, HCT116, and LoVo." (PMID 25788276, 2015). "Two angiogenic growth factors, in particular, Vascular endothelial growth factor (VEGF) and Prokineticin1(PROK1), are considered to have an important role in hematogenous metastasis of colorectal cancer." (PMID 25788276, 2015). "The angiogenic and proliferative effects of PROK1 might contribute to poorer cancer-related survival in patients with pancreatic cancer and colorectal cancer." (PMID 37070074, 2023). "With further therapeutic development, we believe that the anti-PROK1 antibody could be used to control and treat hematogenous metastases in colorectal cancer." (PMID 38275664, 2023). "Given the autocrine effect of PROK1 and its involvement in cell proliferation, in the present study, we investigated the effect of treatment with our PROK1 antibody on the proliferation ability of liver metastases in a mouse colorectal cancer model." (PMID 38275664, 2023). "The anti-PROK1 monoclonal antibody developed by our department is a neutralizing antibody that has been proven to inhibit the angiogenic and subcutaneous tumorigenic potentials in colorectal cancer cell lines." (PMID 38275664, 2023). "Furthermore, we identified a new relationship between PROK1 expression and lymphatic formation, invasion, and metastasis in human colorectal cancer." (PMID 34262649, 2021). "Also a high-PROK1-expressing colorectal cancer cell line and anti-PROK1 antibody(Ab) were subcutaneously implanted in mice, and then examine lymphangiogenesis." (PMID 34262649, 2021).
colorectal cancer (continued). "Recent studies reported that PROK1 expressed not only endocrine glands but also some malignant tumors, including prostate cancer, pancreatic cancer, ovarian cancer, adrenocortical tumors, and colorectal cancer." (PMID 34657605, 2021). "Moreover, PROK1 was shown to be up-regulated in several types of cancers, such as colorectal cancer, pancreatic cancer, prostate cancer, and ovarian cancer, and was regarded as a poor prognostic marker and survival factor." (PMID 26828479, 2016). "According to subsequent reports, the post-resection prognosis was significantly poorer for colorectal cancer patients with positive PROK1 mRNA expression than for PROK1-negative patients, and PROK1 protein was found to be involved in angiogenesis and lung metastasis from colorectal cancers." (PMID 26318037, 2015). "Subsequently, PROK1 was found to be strongly expressed in a number of malignant tumors including prostate cancer, neuroblastoma, pancreatic duct cancer, thyroid cancer, and colorectal cancer, and a relationship with the level of malignancy was confirmed." (PMID 26372733, 2015). "Simultaneous targeting of both angiogenic growth factors(VEGF/PROK1) may prove more useful in colorectal cancer." (PMID 25788276, 2015). "Also, tumor masses were produced in mice by subcutaneously embedding colorectal cancer cells with high levels VEGF/PROK1 expression." (PMID 25788276, 2015). "As very few studies have been conducted to determine the effects of various angiogenic growth factors, we decided to examine the interactions between VEGF and PROK1, which are two important angiogenic growth factors for hematogenous metastasis in colorectal cancer." (PMID 25788276, 2015). "In human colorectal cancers, PROK1 and VEGF are important factors for invasion and metastasis." (PMID 26318037, 2015). "Cancer cell growth or progression is considered consequent to the overexpression or deficiency of various factors and no reports have been published on the simultaneous investigation of VEGF and PROK1, both of which are substantially involved in the hematogenous metastasis of colorectal cancer." (PMID 26318037, 2015). "Moreover, PROK1 expression is a prognostic factor in colorectal cancer." (PMID 38275664, 2023). "However, it is unclear whether the concentration of PROK1 in the blood of patients can be used as a new prognostic biomarker for patients with colorectal cancer." (PMID 34657605, 2021). "Meanwhile, our study involving a colorectal cancer cell line with low levels of Prokineticin1(PROK1) expression showed that angiogenesis, tumor proliferation, and hematogenous metastasis occurred at high rates in the surrounding tissues when the PROK1 gene was introduced." (PMID 25788276, 2015). "For Stage IV colorectal cancer patients, the 5-year survival rate was 16.1% among cases that expressed either VEGF or PROK1 protein and 5.1% among cases that expressed both proteins." (PMID 26318037, 2015). "When the culture fluid of Colorectal cancer cell lines(DLD-1, HCT116, and LoVo) with high levels of VEGF/PROK1 expression was injected subcutaneously into mice, the culture fluid increased subcutaneous angiogenesis." (PMID 25788276, 2015). "The plasma PROK1 level may be a potential predictive marker, especially in stage III colorectal cancer patients." (PMID 34657605, 2021). "VEGF and PROK1 expression in 620 primary human colorectal cancer lesions was confirmed via immunohistochemical staining with anti-VEGF and anti-PROK1 antibodies, and the correlation between the expression of these 2 proteins and recurrence/prognosis were investigated." (PMID 26318037, 2015). "Both VEGF and PROK1 have been confirmed as significant factors in colorectal cancer, though expression of the two factors has not been investigated in this context." (PMID 25788276, 2015).
colorectal cancer (continued). "Thus far, PROK1 has been shown to promote cancer cell proliferation by interacting with MAP kinase through the PROK1 receptor, which is expressed on the surface of the membrane of colorectal cancer cells." (PMID 38275664, 2023). "Notably, while PROK1 staining is not observed in the normal mucosa of the large intestine, it is present in the cytoplasm of cells in approximately 40% of colorectal cancers." (PMID 38275664, 2023). "The 5-year survival rates for all colorectal cancer patients were 91.3% among cases with no VEGF/PROK1 expression, 76.4% among cases that expressed either protein, and 57.3% among cases that expressed both proteins; the latter rate indicated a significantly poorer prognosis." (PMID 26318037, 2015).
prostate carcinoma (7 papers, 2015 to 2026). A carcinoma that arises from epithelial cells of the prostate gland. "This critical distinction underscores the importance of the cellular and molecular microenvironment in determining PROK1's ultimate functional outcome and highlights its potential as a novel therapeutic target specifically for prostate cancer." (PMID 41584032, 2026). "PROK1 expression also reportedly correlated with cancer progression and metastasis in pancreatic duct cancer, prostate cancer, neuroblastoma, and several other malignant tumors." (PMID 26318037, 2015). "Other institutions reported the relationship between PROK1 expression and malignancy in prostate cancer, neuroblastoma, and pancreatic cancer." (PMID 25788276, 2015). "To investigate whether PROK1 is involved in the regulation of prostate cancer through the apoptotic pathway, we added copper ions to the culture medium of the PC3 cell line to induce cuproptosis." (PMID 41584032, 2026). "Other studies demonstrated that PROK1 expression correlates with malignancy in prostate cancer, neuroblastoma, thyroid cancer, pancreatic duct cancer, gastric cancer, and small intestinal cancer, indicating that PROK1 is important for malignant tumor formation." (PMID 34262649, 2021). "Also, PROK1 levels were reported to be related to the degree of malignancy in gastric cancer, small intestine cancer, pancreatic cancer, neuroblastoma, and prostatic cancer." (PMID 25788276, 2015).
neuroblastoma (5 papers, 2015 to 2023). Neuroblastoma (NB) is the most common solid, extracranial childhood tumor. "Recent studies demonstrate the expression of PROK1 in digestive tract cancer (gastric, small intestine, etc.), as well as in neuroblastoma, thyroid cancer, and pancreatic duct cancer." (PMID 34262649, 2021). "In neurons, PROK1, but not PROK2, enhances cell migration of the human neuroblastoma cell line SK-N-SH at high concentrations (400 nM)." (PMID 37895111, 2023).
pancreatic cancer (5 papers, 2015 to 2026). "PROK1 knockdown also inhibited the proliferation of pancreatic cancer cells, characterized by a decrease in PCNA and cyclin D1 levels, leading to slow growth of PC in vivo." (PMID 37070074, 2023). "Our results showed that PROK1 knockdown inhibited pancreatic tumor growth in vivo and reduced proliferating markers, such as PCNA and cyclin D1, at the molecular level." (PMID 37070074, 2023). "The PI3K/AKT/mTOR (phosphatidylinositol 3-kinase/protein kinase B/mammalian target of rapamycin) pathway can be initiated by PROK1 (prokineticin 1), but its effect and mechanism of action in pancreatic carcinoma (PC) are not fully understood." (PMID 37070074, 2023). "Also, the six related genes, such as VMW, might be important for evaluating the effects of PROK-1 knockdown in pancreatic cancer cells, and further experiments were required to elucidate their role." (PMID 37070074, 2023). "Therefore, PROK1 might be a potential molecular target for pancreatic cancer therapy, and further studies on it, along with its related genes, might be valuable for treating pancreatic cancer." (PMID 37070074, 2023). "Previous studies have shown that silencing PROK1 exerts its anti-pancreatic cancer effects by inhibiting the PI3K/AKT/mTOR pathway, leading to increased levels of Bax and Cleaved Caspase 3, and decreased levels of PCNA and Bcl-2 in pancreatic cancer cells." (PMID 40961099, 2025).
endometriosis (4 papers, 2021 to 2025). The growth of functional endometrial tissue in anatomic sites outside the uterine body. "Of these genes, PROK1 (Prokineticin 1) has been suggested to be associated with endometriosis due to its role in promoting angiogenesis." (PMID 37662927, 2023). "In addition, some identified hub genes of the EC (TAGLN, GATA6, CDH3, CLU, COL8A1, MYH11, MYOCD) and EU (CXCL13, DDK-1, KLF4, CYP2E1, CYP4B1 and PROK1) have been reported be associated with endometriosis." (PMID 34522169, 2021). "Dysregulated endometrial PROK1 expression may be correlated with the progesterone resistance of endometriosis." (PMID 34522169, 2021). "For instance, prokineticin-1 (PROK1), which is important in the vascular function of peri-implantation endometrium and early pregnancy, is significantly less expressed in the eutopic endometrium of patients with endometriosis." (PMID 36171908, 2022).